EPCAM (epithelial cell adhesion molecule)
Diseases named in the same sentence as EPCAM in open-access papers (continued):
Sharing a sentence is not in itself a finding about the gene and the disease.
head and neck squamous cell carcinoma (26 papers, 2007 to 2026). A squamous cell carcinoma that arises from any of the following anatomic sites: lip and oral cavity, nasal cavity, paranasal sinuses, pharynx, larynx, and salivary glands. "It was demonstrated that higher incidence of intense expression of EpCAM was found in head and neck squamous cell carcinoma (HNSCC) from the hypopharynx, and patients with strong EpCAM expression were associated with local recurrence after primary RT." (PMID 30419852, 2018). "Our group has previously developed a highly sensitive, specific and robust RT-qPCR assay of PD-L1 mRNA expression and we reported its clinical utility in EpCAM-positive CTCs of head and neck squamous cell carcinoma patients." (PMID 33668490, 2021). "We have investigated the link between EpCAM and the Nrf2 pathway in light of therapeutic resistance using head and neck squamous cell carcinoma (HNSCC) patient tumor samples and cell lines." (PMID 32814771, 2020). "In previous studies, EpCAM was established as an adverse prognostic factor for radiotherapy in head and neck squamous cell carcinoma patients." (PMID 33490064, 2020). "In our previous study, we demonstrated that targeting three epithelial-related markers, EpCAM, epidermal growth factor receptor (EGFR), and MET, increased the CTC detection rate in patients with head and neck squamous-cell carcinoma (HNSCC)." (PMID 40699639, 2025). "HNSSC (Squamous cell carcinoma of the head and neck) xenotransplanted severe combined immunodeficient (SCID) mice were treated with radioimmunotherapy against EpCAM positive cells and biodistribution of EpCAM-directed monoclonal antibodies were investigated in EpCAM-transgenic mouse models." (PMID 22590529, 2012). "Of note, the glycosylation grade of EpCAM derived from head and neck squamous cell carcinomas varied, and it is as yet unclear whether weakly or non-glycosylated EpCAM variants may appear on other tumours." (PMID 17622246, 2007).
lymph node metastasis (26 papers, 2005 to 2025). "EpCAM overexpression was significantly positively associated with lymph node metastasis (p = 0.01), clinical stage (p = 0.02), while negatively associated with smoking status (p = 0.02)." (PMID 26698569, 2015). "EpCAM-positive CTCs are associated with poor prognosis, very low overall survival, and the presence of lymph node metastases." (PMID 26317650, 2015). "However, one would be hard-pressed to explain how lymph node metastasis is inversely associated with the expression of EpCAM." (PMID 34680248, 2021). "Interestingly, EpCAM-positive DTCs of esophageal cancer patients strongly associated with lymph node metastases and poor OS, but represented a minority in these patients, with approximately two-thirds bearing EpCAM-negative DTCs." (PMID 27683128, 2017). "cCAF positivity was significantly associated with lymph node metastasis, CTC positivity, and lower EPCAM levels on CTCs." (PMID 40616388, 2025). "This supports the significant results between prevalence of EpCAM expression and the presence of both distant metastasis and lymph node metastasis in our study." (PMID 32212818, 2020). "Prevalence of EpCAM positivity gave significant results with distant metastasis, lymph node metastasis, and portal vein thrombosis." (PMID 32212818, 2020). "These lymph nodes were found to be free of metastases at routine histopathological examination, showing the use of antibodies against EpCAM was highly sensitive in the detection of lymph node metastases." (PMID 28820475, 2017). "It was found that EpCAM overexpression was related to tumour size and lymph node metastasis in GC patients." (PMID 28403178, 2017). "EpCAM has proved to be a target with high sensitivity (100%) and specificity (100%) for lymph node metastases and high sensitivity (95%) and specificity (100%) for bone metastases." (PMID 27690012, 2016). "EpCAM was expressed in 100% of lymph node metastases (21 out of 21), in 0% of normal lymph nodes (0 out of 21), in 95% of bone metastases (19 out of 20), and in 0% of normal bone (0 out of 14)." (PMID 27690012, 2016). "Consistent with our study, reports have showed that clinical stage and lymph node metastasis of cancer patients were correlated with EpCAM expression, and EpCAM independently predicted poor overall survival in multivariate analysis." (PMID 26698569, 2015). "Tumors with higher EpCAM expression at the invasive front, exhibited a significantly higher proportion of lymph node metastases and a significantly decreased overall survival, which was of independent prognostic impact." (PMID 23830302, 2013). "In multivariate analysis, EPCAM expression was an independent prognostic factor, along with histology and lymph node metastasis." (PMID 24422715, 2013). "EpCAM overexpression was not linked to pT stage and lymph node metastasis, but was associated with Gleason score and bone metastasis." (PMID 31324239, 2019). "Median EpCAM expression (TIS) in lymph node metastases was 5.0 (inter quartile range: 2.0–8.0)." (PMID 28820475, 2017). "Eighty-five percent (n=75) of lymph node metastases were positive for EpCAM." (PMID 23830302, 2013). "However, there are some other studies in the literature which have suggested the negative association of EpCAM expression with tumor grade, invasion, and lymph node metastasis and noted the correlation of a decreased expression of EpCAM with poor survival and cancer recurrence in CRC patients." (PMID 35016698, 2022). "Moreover, the prognostic value of EpCAM only applied to patients with lymph node metastasis." (PMID 31443698, 2019). "However, EpCAM expression in lymph node metastases is sparsely available in the literature and EpCAM expression in bone metastases is yet unknown." (PMID 27690012, 2016). "We demonstrated that EpCAM and MGST1 were abundantly expressed in LSCC, particularly in cases with lymph node metastasis." (PMID 40778224, 2025).
lymph node metastasis (continued). "Our results revealed that in samples with higher counts of EpCAM+ tumor cells, the expression of HLA-G, ILT-2, ILT-4, and PD-L1 was significantly related to distant lymph node metastasis, advanced disease stage, and shorter patient survival." (PMID 34054869, 2021). "Consistent with this notion, a higher percentage of CD133+/EpCAM+ CSCs that express PD-L1 were observed in the lymph nodes of NSCLC patients with lymph node metastasis when compared with patients without lymph node metastasis." (PMID 38765006, 2024). "The current study is the first to compare EpCAM expression between matched normal lymph nodes and lymph node metastases and to evaluate EpCAM expression in bone metastases and normal bone." (PMID 27690012, 2016). "Next, in order to address the specificity of these results, the expression of EpCAM protein, another membrane-localized stem cell marker, was examined by immunohistochemistry with serial sections of the same slides obtained from the HGOC group with lymph node metastasis." (PMID 35159173, 2022). "Furthermore, TCGA data showed that EpCAM overexpression was not closely correlated with age, pT stage, lymph node metastasis, number of lymph node, prostate-specific antigen level, Gleason score, biochemical recurrence, and overall survival." (PMID 31324239, 2019). "In addition, it was noted that, unlike EpCAM, the differential expression of MGST1 was only observed in cases with lymph node metastasis compared to cases without metastasis." (PMID 40778224, 2025).
esophageal cancer (25 papers, 2010 to 2023). A primary or metastatic malignant neoplasm involving the esophagus. "Moreover, in migrating esophageal carcinoma cells and in head and neck carcinoma cells, a progressive loss of EpCAM expression occurs at the membrane with the appearance of EpCAM positive speckles in the cytoplasm, suggesting EpCAM endocytosis and degradation." (PMID 31225512, 2019). "This is in contrast to previous studies on esophageal cancer, in which most LN‐DTCs were EpCAM‐positive." (PMID 34719102, 2022). "During TGF-β1-induced EMT in esophageal cancer cells, EpCAM expression on the surface of the cell membrane was substantially reduced, together with enhanced migration, invasion and dissemination ability." (PMID 36369033, 2022). "In early esophageal cancer, decreased expression of EpCAM was found to induce EMT, thus promoting metastasis." (PMID 36369033, 2022). "Next, EMT was induced in the EpCAM-positive esophageal carcinoma cell line Kyse30 upon treatment with TGFβ." (PMID 34693227, 2021). "Here, we demonstrate a partial loss of EpCAM expression upon mesodermal differentiation of ESC and following induction of EMT by TGFβ in esophageal carcinoma cells." (PMID 34693227, 2021). "With the use of cytokeratin as an additional enrichment target, the CTC detection rate in esophageal cancer patients can be elevated and displays the heterogeneity of cytokeratin (CK) and EpCAM expression." (PMID 32197486, 2020). "Blood samples from 90 esophageal cancer patients were analyzed using a combined cytokeratin/EpCAM enrichment." (PMID 32197486, 2020). "The main targets for CARs of esophageal cancer were epithelial cell adhesion molecule (EpCAM) and HER2." (PMID 31936611, 2020). "In esophagus cancer, high EpCAM expression has been correlated with proliferative stages, whereas low or negative expression was associated with cancer cell migration, invasion and dissemination." (PMID 32764280, 2020). "At present, the FDA approves the automated cell detection method for EpCAM as biomarker, and this method has been used to detect circulating tumor cells in patients with breast, prostate and esophageal cancer." (PMID 31443698, 2019). "Direct involvement of EpCAM in the migratory phenotype of esophageal carcinoma was tested upon siRNA-mediated downregulation of EpCAM." (PMID 31225512, 2019). "For example, expression of EpCAM on DTCs of esophageal cancer patients was restricted compared to primary tumors, but correlated with lymph node involvement and remarkably poor outcome." (PMID 27683128, 2017). "The recent report on EpCAM expression in early systemic esophageal cancer also supports our findings." (PMID 27421772, 2016). "Recently, a dynamic expression of EpCAM was reported in esophageal cancer throughout tumor progression." (PMID 27421772, 2016). "This study tested, for the first time, the ability of EpCAM aptamer SYL3C to detect EpCAM expression in 170 cases of esophageal cancer (EC) and precancerous lesions, as well as 20 cases of EC series samples, using immunofluorescence imaging analysis." (PMID 26687301, 2015). "EPCAM expression in human esophageal cancer correlated with tumor depth, stage, blood-vessel invasion and infiltrative growth pattern." (PMID 24422715, 2013). "However, during the TGF-β1-induced EMT of esophageal cancer cells, EpCAM expression on the cell surface was substantially reduced." (PMID 36369033, 2022). "However, given the uncertain clinical significance of EpCAM− CTCs in patients with esophageal cancer, we only defined CTCs as Hoechst+CD45−EpCAM+ cells in this study." (PMID 36143225, 2022). "Besides, molecular docking technology demonstrated that Rh2 had a high affinity with epithelial cell adhesion molecule, which was identified as a potential therapy target in esophageal carcinoma, through establishing hydrogen bonding with Leu240." (PMID 34608390, 2021). "Additionally, the number of EpCAM+ DTCs was correlated with significantly lower OS in patients with esophageal cancer." (PMID 32764280, 2020).
esophageal cancer (continued). "A further study identified disseminated tumor cells from bone marrow and lymph nodes in patients with esophageal cancer and, although the primary tumors predominantly expressed high levels of EPCAM, EPCAM expression was only observed in 37% of disseminated tumor cells from bone marrow aspirates." (PMID 28336725, 2017). "Another report on EpCAM expression in surgical specimens from esophageal cancer patients (n = 138), using real-time RT-PCR, IHC and ELISA showed that the mean expression level of EpCAM mRNA in tumor tissues was significantly higher than that in corresponding normal tissues (P<0.0001)." (PMID 21152431, 2010). "Currently, the potential targets against esophageal cancer include MUC1, HER2, EpCAM, EpA2 and CD276, for CAR-T cell therapy, NY-ESO-1, MAGE-A3 and MAGE-A4 for TCR-T cell therapy." (PMID 34858843, 2021). "Reduction of EpCAM during mesodermal differentiation and TGFβ-induced EMT correlated with enhanced endocytosis and block or reduction of recycling in ESCs and esophageal carcinoma cells." (PMID 34693227, 2021). "A study on esophageal cancer found that the majority of DTCs in bone marrow lacked EpCAM expression, while EpCAM was strongly expressed in the tumor." (PMID 32764280, 2020). "High EpCAM expression was observed in esophageal cancer tissues and esophageal cancer-derived cell lines, but not in adjacent benign esophageal epithelia and benign esophageal cell lines (HET 1-A and Bar-T)." (PMID 30116994, 2018). "Similar to esophageal cancer DTCs, environmental cues from the BM may drive cancer cells in a non‐proliferative quiescent/dormant state, which agrees with an EpCAM‐poor/negative phenotype." (PMID 34719102, 2022). "Moreover, our results suggest that the CK7/8+/EpCAM+ or CK7/8+/EpCAM− CTC subtype does not lead to an advanced tumor staging tool in non-metastatic esophageal cancer (EC) patients." (PMID 32197486, 2020). "Hence, it can be hypothesized that the metastatic progression of esophageal cancer may be supported by both EpCAM-positive and EpCAM-low/negative cancer cells in a context-dependent manner, and that this different phenotype may also be histotype-specific." (PMID 27527155, 2016). "CK18+ DTCs were detected in 38.9% of esophageal cancer patients, but co-expression of EpCAM was seen in only 37.1% of DTC-positive cases, whereas 62.9% of patients showed CK18+/EpCAM low/negative DTCs." (PMID 27527155, 2016).
bladder cancer (24 papers, 2014 to 2025). "Interestingly, EpCAM overexpression in many different cell line models such as lung, ovarian, colon and bladder cancer has been associated with low invasiveness potential." (PMID 28152020, 2017). "This approach enables the detection of immuno-captured bladder cancer cells by targeting their Epithelial Cell Adhesion Molecule (EpCAM) through the use of specific anti-EpCAM antibodies." (PMID 39771612, 2024). "Due to its expression pattern in TCC, EpCAM is a clinically relevant antigen target for immunotherapy of bladder cancer." (PMID 33837852, 2021). "Oportuzumab is directed against EpCam and fused with Pseudomonas aeruginosa exotoxin A for the treatment of a specific bladder cancer." (PMID 34939999, 2021). "Methods capable of detecting whole bladder cancer cells shed in urine are typically based on cell size, cellular features or the expression of specific proteins (e.g., intracellular galectin-1 or EpCAM)." (PMID 32521780, 2020). "EPCAM was a transmembrane glycoprotein identified with higher expression level in the urine of patients with a higher grade or advanced stage of bladder cancer." (PMID 32640634, 2020). "Urinary EpCAM levels have been identified as robust indicators of bladder cancer-specific survival." (PMID 38665947, 2024). "Several studies described associations between high EpCAM/TROP2 expression and poor bladder cancer prognosis while others found a relationship with favorable tumor features in adenocarcinoma of non-small cell lung carcinoma and upper tract urothelial carcinoma." (PMID 38282671, 2023). "By flow cytometry, we could then assess separately the proportions and effects of BCG on CD45–EpCAM+ bladder cancer cells and CD45+EpCAM– WBCs from the same tumors." (PMID 35503263, 2022). "We have previously reported the identification of the shed ectodomains of HAI-1, EpCAM and EGFR in the urine of bladder cancer patients; elevated urine levels of the shed ectodomains of EpCAM and EGFR are associated with worse bladder cancer (BC) specific survival." (PMID 29861867, 2018). "Based on this study, EpCAM could be used as an imaging target for bladder cancer lymph node metastases." (PMID 28820475, 2017). "The continuous decrease of TROP2 and EpCAM expression with grade in non-invasive urothelial bladder carcinomas in combination with the somewhat higher expression levels – to the degree of pTa G2 – in pT2-4 carcinomas could be explained by the unique evolution of pTa bladder cancers in vivo." (PMID 38282671, 2023). "Urinary levels of HAI-1, EpCAM and EGFR were measured by ELISA in 683 and 175 patients with newly-diagnosed NMIBC and MIBC, respectively, recruited to the Bladder Cancer Prognosis Programme." (PMID 29861867, 2018). "Both proteins share partial overlapping functions in epithelial development and EpCAM expression but have not been comparatively analyzed together in bladder carcinomas." (PMID 38282671, 2023). "In accordance with the binding results, catumaxomab-induced cytotoxicity against EpCAM-positive bladder cancer cells was not diminished in 10% vol." (PMID 33837852, 2021). "Recently, the use of improved AdnaTest immune-magnetic systems also allowed the identification of CTC with stem-like features by PCR-based methods, showing that ALDH1 mainly contributed to CTC positivity compared to EPCAM, MUC1, or ERBB2 in bladder cancer patients." (PMID 28321147, 2017).
bladder cancer (continued). "The absence of EpCAM overexpression in normal lymph nodes supports the use of EpCAM as a target for bladder cancer lymph node metastases." (PMID 28820475, 2017). "Despite these evidences, the glycosylation pattern of EpCAM in bladder cancer has also not yet been evaluated." (PMID 29207682, 2017). "Further comparative analysis performed on the overlayed binding histograms demonstrated that anti-EpCAM bound strongly to SK-BR-3, weakly to T24, but not to SK-Mel-28 cells, indicating that breast and bladder cancer cells had high and medium expression of EpCAM, respectively." (PMID 26267323, 2015).